EIF3A (eukaryotic translation initiation factor 3 subunit A)
Diseases named in the same sentence as EIF3A in open-access papers (continued):
Sharing a sentence is not in itself a finding about the gene and the disease.
EIF3A also shares sentences with these, for which no sentence is quoted: cervical cancer (7 papers); neurodegenerative disease (4); head and neck squamous cell carcinoma (3); leukemia (3); neurological disorders (3); Parkinson disease (3); chronic myelogenous leukemia (2); esophageal squamous cell carcinoma (2); glioblastoma (2); infectious disease (2); stomach cancers (2); Acute hepatitis (1); acute lymphoblastic leukemia (1); amyotrophic lateral sclerosis (1); astrocytomas (1); atherosclerosis (1); autoimmune disease (1); autosomal-recessive intellectual developmental disorder 67 (1); bladder urothelial carcinoma (1); brain disorder (1); Breast Invasive Carcinoma (1); Calicivirus infections (1); colon adenocarcinoma (1); convulsion (1); Ebola (1); endometrial cancer (1); epilepsy (1); fibrosis (1); frontotemporal dementia (1); gallbladder cancer (1).
A further 32 diseases each share a sentence with EIF3A in 1 paper.